GPC4 (glypican 4)
Diseases named in the same sentence as GPC4 in open-access papers (continued):
Sharing a sentence is not in itself a finding about the gene and the disease.
renal carcinoma (1 paper, 2024). A carcinoma arising from the epithelium of the renal parenchyma or the renal pelvis. "The results of immunohistochemical analysis indicate that the expression levels of COL9A3, GPC4, and ITGA6 in renal cancer tissue are higher than those in normal tissue, whereas the expression levels of FREM2, ITGA9, and P3HI are lower than in normal tissue." (PMID 38365923, 2024).
Renal insufficiency (1 paper, 2021). A reduction in the level of performance of the kidneys in areas of function comprising the concentration of urine, removal of wastes, the maintenance of electrolyte balance, homeostasis of blood pressure, and calcium metabolism. "Patient with renal insufficiency showed increased levels of GPC-4 as well as a negative association of GPC-4 levels with GFR and a positive correlation with urinary albumin excretion." (PMID 34903856, 2021).
tumor (18 papers, 2015 to 2025). "Some DEGs like FREM2, ANXA2 and GPC4 revealed common enrichment in LE/IT tumor regions across GBM patient samples compared to the overall downregulation of the OPC/OL marker MBP, the neural marker NTRK2, and the ECM glycoprotein EDIL3." (PMID 41366031, 2025). "So glypican-1 and glypican-6 serve largely as tumour promoters, and glypican-3, and glypican-4 inhibit BC." (PMID 41463344, 2025). "In recent years, glypican-4 has been described for the first time as having a tumour-suppressive potential, in the sense that downregulation would favour progression of the BC." (PMID 41463344, 2025). "Further, the distinct and diverse effects of GPC4 on the progression of different cancers propose its pleiotropic effect on the tumor microenvironment and oncogenic signaling." (PMID 38612755, 2024). "While GPC1 and GPC2 exhibited a strong net upregulation in tumor samples over normal across the board of cancer types, other members like GPC4, GPC5, and GPC6 were characterized by tissue-specific cancer expression patterns." (PMID 36944188, 2023). "To test our idea, we generated GPC4-overexpressed plasmids to examine the importance of GPC4 in CD36-mediated tumor-suppressive function." (PMID 31484922, 2019). "Taken together, these results further suggested the molecular mechanism by which CD36 controls tumor proliferation and glycolysis via inhibiting GPC4-mediated β-catenin/c-myc signaling in colorectal tumorigenesis." (PMID 31484922, 2019). "For this reason, the determination of the tumor marker CEA together with markers of organ dysfunction such as SDC1 or GPC4 may appear advantageous in estimating the prognosis of CRC since they can provide complementary information." (PMID 36353562, 2022). "Hence, our results suggested GPC4 was indispensable for CD36-mediated tumor-suppressive functions in CRC cells." (PMID 31484922, 2019). "Recently, in BC cell lines, it has been suggested that EGFR and JAK/STAT pathways influence the expression of multiple glypicans (including glypican-1 and glypican-4), indicating that extracellular signal-regulated networks might regulate glypican expression and hence tumour behaviour." (PMID 41463344, 2025). "The results of GEPIA analysis showed that expression of GPC1, GPC3, GPC4, and GPC6 was significantly higher in PDAC tumor tissues than in normal tissues (P < 0.05)." (PMID 33302876, 2020). "The remaining 8 PGs, for which transcripts were expressed at a frequency of 84% (GPC1), 86% (GPC3), 88% (GPC4), 70% (GPC6), 100% (SDC1), 94% (SDC2), 93% (SDC3) and 95% (SDC4) of the tumour cases, respectively, were found to be differently modulated." (PMID 25935541, 2015). "Herein, GPC4 was reported to be an indispensable downstream effector of CD36 and ectopic GPC4 expression could reverse the tumor suppressive and glycolysis inhibitory functions of CD36 by activating β-catenin/c-myc signaling in CRC cells." (PMID 31484922, 2019). "Mechanically, the tumor-suppressive effects of CD36 were mediated through promoting the proteasome-dependent ubiquitination of GPC4, and the degraded GPC4 failed to activate β-catenin/c-myc signaling cascades and downstream glycolytic target genes GLUT1, HK2, PKM2 and LDHA." (PMID 31484922, 2019). "Therefore, circulating SDC1 and GPC4 might be markers of general organ dysfunction rather than specific tumor markers." (PMID 36353562, 2022). "Moreover, the expressions of GPC-1, GPC-2, GPC-4, GPC-5, and GPC-6 were not significantly different between tumor and normal liver tissues." (PMID 33902495, 2021).
cancer (8 papers, 2020 to 2024). A tumor composed of atypical neoplastic, often pleomorphic cells that invade other tissues. "The increased plasma level of GPC4 in these cancers was found to be associated with poor patient survival." (PMID 38612755, 2024). "Survival analysis using TCGA cancer patient data reveals divergent effects of GPC4 expression across various cancer types, revealing elevated GPC4 expression levels to be associated with both poor and favorable prognoses in a cancer-dependent manner." (PMID 38612755, 2024). "We then couple these results with a survival analysis of public cancer data, allowing us to link clinical outcomes with GPC4 expression-associated changes in cancer growth." (PMID 38612755, 2024). "Utilizing clinical patient data from TCGA cohorts, we discovered that GPC4 exhibits a cancer-specific gene expression pattern associated with cancer progression and patient survival." (PMID 38612755, 2024). "Studies on GPC4 in cancer are rather limited and a significant association between plasma GPC4 and the outcome of CRC patients has not been described so far." (PMID 36353562, 2022). "However, the association between circulating GPC4 and the prognosis of patients with mCRC or other types of cancer is unknown so far." (PMID 36353562, 2022). "In this investigation, we have systematically exploited the influence of GPC4 in cancer by creating a comprehensive profile of its expression pattern in normal and malignant tissues across a broad range of cancers." (PMID 38612755, 2024). "Together, these findings emphasize the multifaceted impact of GPC4 in cancer and stress its potential as a biomarker in particular cancer types." (PMID 38612755, 2024). "Our findings illuminate the pleiotropic effect of GPC4 in cancer, underscoring its potential as a putative prognostic biomarker and indicating its therapeutic implications in a cancer type dependent manner." (PMID 38612755, 2024). "In order to gain insights into the potential mechanisms through which GPC4 can confer cancer phenotypes, we systematically compared differentially expressed genes between GPC4-low and GPC4-high subjects across TCGA cancer types." (PMID 38612755, 2024). "Within the GPC family, GPC4 stands out as a less studied but intriguing member, warranting a closer examination of its role in cancer progression." (PMID 38612755, 2024). "The analysis, presented as a volcano plot, exhibits significant differences in GPC4 expression levels between normal and cancer tissues in a wide range of cancers." (PMID 38612755, 2024). "Although our understanding of the involvement of GPC4 in cancer is limited, an increasing body of evidence illustrates its essential role in cancer progression." (PMID 38612755, 2024). "A TCGA cancer patient database was used to investigate the direction, magnitude, and significance of GPC4 gene (GPC4) expression differences between cancer and normal tissues across 24 TCGA cancer types." (PMID 38612755, 2024). "Understanding the intricate effects of GPC4 on neoplastic behavior provides insights into its potential as a prognostic factor and therapeutic target in specific cancer types." (PMID 38612755, 2024). "Further research is essential to unravel the intricate molecular interactions of GPC4 in different cancer contexts, paving the way for a better understanding of its therapeutic implications and diagnostic value." (PMID 38612755, 2024). "Here, we have systematically assessed the impact of GPC4 on cancer progression through functional genomics and transcriptomic analyses across a broad range of cancers." (PMID 38612755, 2024). "Recent preclinical and clinical reports demonstrate the implications of GPC4 in several cancers, including pancreatic, breast, and colorectal cancer." (PMID 38612755, 2024). "In order to explore the impact of GPC4 on cancer survival, we performed a Cox Proportional Hazard (CoxPH) regression against GPC4 expression levels for each TCGA project." (PMID 38612755, 2024).
cancer (continued). "GPC4 is described as being involved in the 5-fluorouracil (5-FU) chemoresistance and stem cell–like properties of cancer cells." (PMID 34249755, 2021). "GPC4 belongs to the glypicans family, a family of heparan sulfate proteoglycans that are attached to the cell membrane via a glycosylphosphatidylinositol anchor, with a known role in cancer." (PMID 36768928, 2023). "The mechanism of action of GPC4 in cancer is also relatively unknown." (PMID 38612755, 2024). "As an attempt to gain insights into the potential mechanisms through which GPC4 confers cancer, we performed an IPA pathway analysis of genes that were differentially expressed between GPC4-low and GPC4-high patients across TCGA cancer types." (PMID 38612755, 2024). "Here we outlined the remarkable features of HSPGs, such as GPC1, GPC4, GPC5, SDC1, SDC2, SDC3 and HSPG2, and some HSPG-related proteins like heparanase and SULF1/2, in cancer diagnosis." (PMID 34249755, 2021). "Studies show that GPC4 influences various mitogenic signaling pathways including TGF-β, TLR4/NF-kB, Wnt, Mmp14, and FGF2, all of which have the potential to affect cancer progression." (PMID 38612755, 2024). "However, concerning the limited knowledge of shed GPC4 on cancer prognosis, the molecule should not be neglected and deserves further investigations." (PMID 36353562, 2022). "Compared with GPC-1, GPC-2, GPC-3, and GPC-5, few studies have investigated the mechanism and prognostic significance of GPC-4 and GPC-6 expressions at the mRNA level in malignant tumors, and no related reports have been found in HCC." (PMID 33902495, 2021). "However, a connection between GPC4 and FGF5 or TGF-β in cancer patients has never been reported before." (PMID 38612755, 2024).
metabolic disorders (4 papers, 2020 to 2025). "Glypican-4 also functions as an adipokine, which is associated with metabolic disease." (PMID 33926070, 2021). "The comparative analysis of ROC curves revealed that the Glypican-4/Fat Body Mass (%) ratio is a good predictor of metabolic disorders (with an 82% specificity level at the cut-off point being 70.00 pg/mL/%)." (PMID 39062482, 2024). "The highest predictive value for metabolic disorders was shown by the Glypican-4/Fat Body Mass (%) (AUC = 0.837) ratio, which had high sensitivity and specificity, with the cut-off point being 71.00 pg/mL/%." (PMID 39062482, 2024). "These metabolic disorders were hypothesized to be induced by elevated levels of mRNA expression of T-box 15 (Tbx15) and glypican 4 (Gpc4) in subcutaneous and visceral adipose tissues respectively." (PMID 32435260, 2020).
cardiovascular disease (3 papers, 2023 to 2025). "Recent analyses of serum GPC-4 in patients with cardiovascular disease corroborate this correlation." (PMID 38424123, 2024). "The lack of obvious sex differences in GPC4, both in expression and in function in our study, may be explained by the fact that HUVECs are not influenced by circulating sex hormones, which play a central role in sex differences in cardiovascular disease." (PMID 37511353, 2023).
kidney disease (3 papers, 2022 to 2024). "The value of GPC4 as a new biomarker for kidney malfunction and kidney disease progression has to be further evaluated in subsequent studies." (PMID 35715556, 2022). "Glypican-4 and adiponectin werelinked to renal function and may be able to forecast the course of renal disease." (PMID 38497075, 2024). "Therefore, functional studies are needed to understand the biological role of circulating GPC4 in kidney disease." (PMID 35715556, 2022).
GPC4 also shares sentences with these, for which no sentence is quoted: Hyperglycemia (3 papers); Hyperinsulinemia (2); skeletal dysplasia (2); /malformation syndrome (1); androgen excess (1); aneurysm (1); autism (1); autosomal recessive intellectual disability (1); Beckwith-Wiedemann syndrome (1); bladder carcinoma (1); brain glioblastoma (1); cartilage disease (1); colon adenocarcinoma (1); colorectal tumors (1); corticobasal degeneration (1); Denys-Drash syndrome (1); embryonal tumors (1); endocervical carcinoma (1); endothelial dysfunction (1); glioma (1); glucose metabolism disorder (1); growth disorders (1); head and neck squamous cell carcinoma (1); hepatocellular carcinoma (1); hereditary multiple exostoses (1); hyperphosphatemia (1); Hypertension (1); Immunodeficiency (1); intraductal papillary mucinous neoplasm (1); kidney chromophobe (1).
A further 19 diseases each share a sentence with GPC4 in 1 paper.